LGALS3 (galectin 3)
Diseases named in the same sentence as LGALS3 in open-access papers (continued):
Sharing a sentence is not in itself a finding about the gene and the disease.
thyroid cancer (continued). "Belonging to the galectin family of β-galactoside-binding proteins, galectin-3 is important when it comes to thyroid cancer, especially when it comes to the diagnosis and prognosis of thyroid nodules." (PMID 38501105, 2024). "Recent research is helping to improve our grasp of galectin-3’s function in thyroid cancer biology and its potential implications for individualized treatment." (PMID 38501105, 2024). "The present study aimed to detect the role of new markers, including galectin-3 (Gal-3) and thyroglobulin (TG), in the prognosis and staging of thyroid cancer." (PMID 35203561, 2022). "In the present study, we aimed to investigate the therapeutic potential of novel galectin-3 inhibitors by treating thyroid cancer cells with different concentrations of GB1107 or TD139." (PMID 34035807, 2021). "Collectively, these results indicate that galectin-3 inhibitors mainly affect anchorage-independent growth and motility of thyroid cancer cells." (PMID 34035807, 2021). "Parallel to the decreased invasive capacity in association with treatment with galectin-3 inhibitors, MMP2 expression progressively diminished when thyroid cancer cells were treated with increasing doses of GB1107 or TD139." (PMID 34035807, 2021). "Accumulating evidence points towards high reliability of the utilization of galectin-3 for thyroid cancer diagnosis at histology." (PMID 34035807, 2021). "Taken together, the AKT/β-catenin pathway is likely involved in the suppression of anoikis resistance and motility in thyroid cancer cells following treatment with galectin-3 inhibitors." (PMID 34035807, 2021). "The migration and invasion abilities of thyroid cancer cells following treatment with galectin-3 inhibitors were further determined." (PMID 34035807, 2021). "Some studies reported that serum galectin-3 levels were higher in thyroid cancer patients, although inconsistencies exist across studies." (PMID 34035807, 2021). "Although previous studies suggest that galectin-3 inhibition led to apoptosis in thyroid cancer cells, we found that this effect was limited to TD139 but not GB1107." (PMID 34035807, 2021). "In conclusion, our study suggested that different galectin-3 inhibitors effectively reduce anoikis resistance and cell migration and invasion in thyroid cancer cells." (PMID 34035807, 2021). "In order to find the possible relationship between the initial thyroidal changes caused by neonatal-irradiation and thyroid tumor development, mRNA expressions of thyroid cancer-related marker genes, Mct8, Lat4, Met, and Lgals3, were determined." (PMID 34880333, 2021). "Lin and colleagues first demonstrated that a small molecule inhibitor of galectin-3 (Td131_1) promoted apoptosis, enhanced chemosensitivity to doxorubicin, and improved radiosensitivity in thyroid cancer cells." (PMID 34035807, 2021). "In conclusion, these novel galectin-3 inhibitors suppressed the anoikis resistance, motility, and invasive capacity of thyroid cancer cells at least partly through the AKT/β-catenin pathway." (PMID 34035807, 2021). "A recent study combining all these data identified the thyroid cancer-specific upregulated genes, such as Met, and Lgals3, which indicated common oncogenic pathways for this cancer." (PMID 34880333, 2021). "In the present study, we aimed to explore the therapeutic potential of novel galectin-3 inhibitors in thyroid cancer." (PMID 34035807, 2021). "Galectin-3 inhibitors are potentially suitable for preclinical evaluation of treatment and/or prevention of metastatic spread in thyroid cancer." (PMID 34035807, 2021). "Galectin-3 (Gal-3), a β-galactosyl-binding molecule in the lectin group, is involved in different biological functions in well differentiated thyroid carcinomas." (PMID 34203725, 2021).
thyroid cancer (continued). "BRAF V600E mutation has been characterized as highly specific for thyroid carcinoma, especially papillary thyroid carcinoma (PTC); human bone marrow endothelial marker-1 (HBME-1) and galectin-3 are also such markers that are highly specific for PTC." (PMID 34934597, 2021). "Galectin-3 in the current study had the highest positive predictive value, negative predictive value, accuracy, and was more specific for the diagnosis of thyroid carcinoma." (PMID 34711014, 2021). "The levels of pre-operative and post-ablative of U-Ex Tg and galectin-3 in patients with thyroid cancer were measured." (PMID 32612576, 2020). "The role of galectin in pancreatic, breast, colon, and thyroid cancer is unclear; in contrast, studies on gastric cancer revealed that it is impossible to use galectin 3 for clinical diagnostics as well as for prediction of disease recurrence and survival." (PMID 32859099, 2020). "Thyroid cancer likely represents the paradigmatic tumor model in which experimental studies on galectins’ glycobiology, in particular on galectin-3 expression and function, contributed greatly to the improvement of cancer diagnosis." (PMID 29393868, 2018). "The method used a thyroid cancer-specific probe obtained by radiolabeling a purified and well-characterized mAb to galectin-3 amino-terminal epitope, with the long half-life positron emitter zirconium-89 (89Zr; t1/2 = 74.8 h, β+ = 22.6%)." (PMID 29393868, 2018). "In the present Special Issue of the International Journal of Molecular Sciences focused on galectins in cancer and translational medicine, other experiences with galectin-1, galectin-3 and thyroid cancer are reported by different research groups." (PMID 29393868, 2018). "Results from this preliminary study showed a good and reliable imaging of galectin-3-positive thyroid tumors between 6 and 9 h from injection of 100 μCi of radiotracer in the tail vein, opening a new avenue in thyroid cancer diagnosis." (PMID 29393868, 2018). "A galectin-3-based thyroid immunoscintigraphy, which used as tracer a 99mTc-labeled mAb to galectin-3 and as detector a prototype of a mini-γ camera for small animal imaging, was used ad hoc for imaging thyroid cancer xenografts in vivo." (PMID 29393868, 2018). "Our group first proposed a novel approach for imaging thyroid cancer in vivo based on galectin-3 immunotargeting." (PMID 29393868, 2018). "These experimental findings clearly demonstrate that galectin-3 likely plays a relevant biological role in thyroid cancer." (PMID 29393868, 2018). "These preliminary results clearly show the real possibility of detecting thyroid cancer in vivo by targeting galectin-3." (PMID 29393868, 2018). "(d) Moreover, a fraction of poorly-differentiated thyroid carcinomas and anaplastic thyroid carcinomas (rare lesions) generally express galectin-3, but lose the ability to uptake radioiodine." (PMID 29393868, 2018). "Galectin-3 is almost invariably expressed in well-differentiated thyroid carcinomas and can be promptly detected in the cytoplasm of malignant thyroid cells by using immunohistochemical procedures." (PMID 29393868, 2018). "This is supported by the fact that thyroid cancer markers Cytokeratin-19 and Galectin-3 detection are strongly reduced upon MEK inhibition." (PMID 28445948, 2017). "Wound healing assays and Transwell assays were then performed to examine the role of Galectin-3 in thyroid cancer cell migration." (PMID 29254179, 2017). "Promoter methylation is a major mechanism of LGALS3 gene silencing also in mucinous colorectal cancers, as well as in pituitary tumors, and breast and thyroid cancer cell lines." (PMID 28481247, 2017). "The literature on Galectin-3 (Gal-3) was systematically reviewed to achieve more robust information on its histologic reliability in identifying thyroid cancers and on the concordance between Gal-3 test in histologic and cytologic samples." (PMID 28800068, 2017).
thyroid cancer (continued). "Galectin-3 is a multifunctional molecule involved in regulation of apoptosis whose potential role as a thyroid cancer marker was recognized by many studies since the first report published in 1995." (PMID 28472764, 2017). "In our previous studies, we had come to a conclusion that Galectin-3 was related to the migration of thyroid cancer cells." (PMID 29254179, 2017). "To further confirm the expression patterns of Galectin-3 in thyroid cancer, we conducted immunohistochemistry in 20 surgical specimens, including 19 pathology-confirmed papillary thyroid cancer samples and 1 anaplastic cancer sample." (PMID 29254179, 2017). "To confirm the phenotype reversion found in PD-325901 treated thyroids, we performed staining for the tumor markers Cytokeratin 19 (CK19) and Galectin-3 (Gal-3), that are clinically used markers of thyroid cancer." (PMID 28445948, 2017). "Knocking down and antagonizing Galectin-3 significantly suppressed the migration of thyroid cancer cells." (PMID 29254179, 2017). "Next, we performed CCK8 assays to examine the effect of Galectin-3 on thyroid cancer cell proliferation." (PMID 29254179, 2017). "In conclusion, our study showed that high expression of Galectin-3 was common in thyroid cancer metastases." (PMID 29254179, 2017). "For thyroid cancers, detection of Galectin-3 expression has been widely used in Fine Needle Aspiration Cytology (FNAC) to help distinguish benign and malignant thyroid nodules." (PMID 29254179, 2017). "Our results mainly revealed that Galectin-3 regulated thyroid cancer cell migration in normoxic and hypoxic microenvironments." (PMID 29254179, 2017). "Based on our findings in immunohistochemistry and western blots of surgical samples, we first supposed that Galectin-3 played a role in the migration and invasion of thyroid cancers." (PMID 29254179, 2017). "Among the various thyroid cancer protein markers, Galectin-3 represents one of the most extensively studied." (PMID 28472764, 2017). "To explore the mechanisms of Galectin-3 regulating the migration and invasion of thyroid cancer cells, we further investigated the effect of Galectin-3 knockdown on several signaling pathways related to cell migration." (PMID 29254179, 2017). "In order to illuminate the effect of Galectin-3 on cancer stem cell properties of thyroid cancers, we performed sphere formation assays in both cell lines." (PMID 29254179, 2017). "In this study, we explored the expression patterns of Galectin-3 in surgical specimens of thyroid cancers, investigated the effect of Galectin-3 inhibition on cell migration and tried to clarify its underlying signaling changes." (PMID 29254179, 2017). "Altogether, knocking down Galectin-3 or blocking its function attenuated the invasion and migration of thyroid cancer cells." (PMID 29254179, 2017). "We next provided evidence that knocking down Galectin-3 reducing the migration and invasion of thyroid cancer cells." (PMID 29254179, 2017). "It was shown that intracellular galectin-3 increased thyroid cancer cells resistance to doxorubicin by activating the PI3K pathway." (PMID 27835877, 2016). "In the cytoplasm, galectin-3 heterodiimerzation with Bax was also found to protect cells against doxorubicin-induced apoptosis in thyroid carcinoma cells." (PMID 27835877, 2016). "Galectin-3 (Gal-3) is an important marker for thyroid carcinomas and a scaffold of the K-Ras protein." (PMID 27551476, 2015). "Galectin 3 plays roles in apoptosis regulation, cell motility, and it is involved in thyroid carcinoma progression." (PMID 26503236, 2015). "The immunohistochemical expression of galectin-3 is currently considered to be the most accurate stand-alone marker for thyroid cancer diagnosis." (PMID 23946782, 2013). "Galectin-3 (Gal-3) has received significant attention and is considered to be the most accurate stand-alone marker for differentiated thyroid cancer diagnosis." (PMID 23946782, 2013).
thyroid cancer (continued). "On the other hand, LGALS3, an IgE-lectin binding protein, is often abundantly expressed in thyroid cancer, hepatocellular carcinoma and in non-small cell lung cancer." (PMID 21909426, 2011). "Kidney and thyroid cancer tissues had high galectin-3 but lower Beclin1 in cancer compared to normal." (PMID 22039439, 2011). "Another study used small molecule inhibition of galectin-3 in thyroid cancer cell lines and showed that inhibition induces apoptosis of the cancer cells and sensitivity to doxorubicin." (PMID 22039439, 2011). "These biomarkers, such as CK19, TG, Ki67, Calcitonin, TTF-1, BRAF, RET, HBME-1, and galectin-3, have been translated into clinical practice which offered significant improvement in the preoperative diagnosis of thyroid cancer." (PMID 22188859, 2011). "In the present study, galectin-3 mRNA levels were highest in breast, lung, kidney, and thyroid cancers when compared to normal tissues." (PMID 22039439, 2011). "In the present study, our finding about the expression of galectin-3 in thyroid carcinomas was less specificity (49.01%)." (PMID 22188859, 2011). "In this study, by using in vivo and ex vivo experimental models of thyroid cancer we show the possibility to obtain a reliable thyroid cancer imaging in vivo by targeting the galectin-3 lectin molecule." (PMID 19020658, 2008). "The use of galectin-3 radiotracer for detection of thyroid cancer in vivo is supported by a solid molecular rationale." (PMID 19020658, 2008). "Altogether these results suggest the possibility to detect thyroid cancer and other galectin-3 expressing tumors in vivo by using a galectin-3 specific radio-immunoscintigraphy." (PMID 19020658, 2008). "Although translation of these findings in the clinical setting will require the use of humanized mAbs linked to different radionuclides and more extensive preclinical studies, we attempted to simulate a galectin-3-based imaging of human thyroid cancer ex-vivo." (PMID 19020658, 2008). "Human galectin-3 positive thyroid cancer xenografts (ARO) and galectin-3 knockout tumors were used as targets in different experiments in vivo." (PMID 19020658, 2008). "The PPV was 78.4% (>92% if galectin-3-positive follicular proliferations UMP are considered as early transformed lesions or ‘thyroid cancer precursor lesions’), whereas the NPV was 98.6%." (PMID 16804521, 2006). "It is noteworthy that all of the five thyroid carcinomas in this group were immunoreactive with the mAb to galectin-3." (PMID 16804521, 2006). "One recent study showed for the first time on a large series of thyroid nodules that galectin-3 as assessed by immunodetection appeared to be a reliable marker of well-differentiated thyroid carcinoma with high sensitivity and specificity." (PMID 16251880, 2005). "Galectin-3 expression is used as a prognostic indication in thyroid cancer." (PMID 38501105, 2024). "Instead, LGALS3 is mostly used as a biomarker for thyroid cancer diagnosis, and given its participation in tumor progression, it is currently under investigation as a potential target for thyroid cancer treatment." (PMID 39519020, 2024). "In particular, LGALS3, the hub protein, may perform a significant role in pediatric thyroid carcinoma." (PMID 38671151, 2024). "Galectin 3 (Gal-3) has received significant attention for its utility as a diagnostic marker for thyroid cancer, being positive in thyroid carcinoma and negative in benign neoplasms and normal thyroid tissue." (PMID 37324272, 2023). "Moreover, β-galactoside-binding protein galectin-3 (Gal-3) is a biomarker, expressed only in thyroid cancer cells." (PMID 35836956, 2022). "Recently, we reported that galectin-3 inhibitors could suppress anoikis resistance and invasive capacity in thyroid cancer cells." (PMID 35723359, 2022). "Accumulating evidence suggests that galectin-3 is a histologic marker of thyroid cancer." (PMID 34035807, 2021).
thyroid cancer (continued). "Therefore, it is intriguing to assess the therapeutic potential of targeting galectin-3 in thyroid cancer." (PMID 34035807, 2021). "In this regard, galectin-3 inhibitor therapy may be incorporated in the treatment or prevention of distant metastasis from thyroid cancer." (PMID 34035807, 2021). "However, as we see in the textbook table, napsin A can be also found in 5% of thyroid cancers as well as galectin 3 can be found up to 50% of lung adenocarcinoma." (PMID 33706755, 2021). "Galectin-3 protein expression in FPTLs: Galectin-3 is a member of the β-galactoside-binding mammalian family of lectins that serves functions in metastasis, angiogenesis, proliferation, and apoptosis of multiple tumor types, including thyroid carcinoma." (PMID 34711014, 2021). "Moreover, in concordance with other studies, our work revealed that HBME-1 and Galectin-3 had the highest sensitivity for the diagnosis of thyroid carcinoma." (PMID 34711014, 2021). "Importantly, the synergistic or coordinating interaction between galectin-3 and caveolin-1 has been reported to promote tumor cell migration and invasion in thyroid cancer." (PMID 31252633, 2019). "Although the preclinical experimental work performed with galectin-3 immuno-PET has been focused on thyroid cancer detection in vivo, the proposed technology could be useful in different tumor conditions." (PMID 29393868, 2018). "The specificity of galectin-3 immuno-PET targeting for imaging thyroid cancer has been further confirmed by an extensive ex vivo biodistribution analysis, measuring the amount of 89Zr-labeled probe accumulated in tumors and normal tissues explanted from the experimental animals." (PMID 29393868, 2018). "Galectin-3 immuno-PET strategy for imaging thyroid cancer in vivo is supported by a strong clinical and biological rationale and has the potential to improve, in the near future, the clinical management of patients bearing thyroid nodules, reducing unnecessary surgery and social costs." (PMID 29393868, 2018). "This study suggests that Galectin-3 could act as a modulator of thyroid cancer migration, especially in hypoxic microenvironments." (PMID 29254179, 2017). "In the same research, they also reported that Galectin-3 and Cav-1 were required for RhoA GTPase activation and knocking down of either Galectin-3 or Cav-1 significantly reduced the migration of differentiated thyroid cancer cells." (PMID 29254179, 2017). "Thyroid cancers with Galectin-3 expression were prone to metastasize in some studies." (PMID 29254179, 2017). "Galectin-3 was highly expressed in metastasized thyroid cancers." (PMID 29254179, 2017). "The aim of this study is to investigate the role of Galectin-3 in human thyroid cancer migration." (PMID 29254179, 2017). "Another interesting molecule expressed by thyroid carcinomas is galectin-3, which has been demonstrated to be overexpressed in more than 94% of thyroid carcinomas, excluding the MTC, while benign thyroid proliferations, such as nodular hyperplasia and adenoma, do not express this marker." (PMID 29258188, 2017). "Additionally, it was demonstrated that the synergistic action of galectin-3 and caveolin-1 induced focal adhesion turnover and migration of differentiated thyroid cancer cells." (PMID 27242966, 2016). "Galectins, especially galectin-3, are suggested to play a role in the pathogenesis of well-differentiated thyroid carcinoma, particularly in papillary carcinoma and, therefore, it is one of the markers most commonly used to assist in distinguishing thyroid lesions." (PMID 22888980, 2012). "The utility of galectin-3 and CK-19 may provide significant contributions in the differential diagnosis of malignant thyroid tumors." (PMID 22188859, 2011). "Breast, kidney and thyroid cancers had high galectin-3 levels and low Beclin1 levels." (PMID 22039439, 2011). "It is important to determine the biological function of galectin-3 in thyroid cancer." (PMID 20652009, 2010).